SRSF3 (serine and arginine rich splicing factor 3)
Diseases named in the same sentence as SRSF3 in open-access papers (continued):
Sharing a sentence is not in itself a finding about the gene and the disease.
cancer (continued). "The mechanisms identified here may help elucidating the role of SRSF3 in malignant transformation as cancer (stem) cells share many features with self-renewing cells." (PMID 29741478, 2018). "Overexpression of SRSF3 is observed in human cervical, breast, ovarian, stomach, skin, thyroid, kidney and bladder cancers, while up-regulation of SRSF6 has been implicated in lung and colon cancers." (PMID 30463359, 2018). "Knockdown of SRSF3 induces cell apoptosis in various types of cancer cells." (PMID 30463359, 2018). "Our results strongly suggest that PTBP1, hnRNPA1, and SRSF3 controlled cancer-specific energy metabolism at least in part through affecting the PKM gene expression profile via AS, which was clarified by RIP and IP assays, and that these proteins coding RNA would be targets for RNA medicine." (PMID 30279379, 2018). "Furthermore, Srsf3 is a proto-oncogene and its expression is frequently dysregulated in cancer cells." (PMID 29741478, 2018). "Taken together, SRSF3 confers malignant phenotypes on cancer cells by upregulating the NF-κB-dependent miR-1908-5p expression and its oncogenic functions are enforced by positive feedback regulation of the NF-κB pathway via the SRSF3/miR-1908-5p/NKIRAS2 axis." (PMID 28039456, 2017). "Hence, SRSF3 is a potential therapeutic target for various cancers." (PMID 38909100, 2024). "In addition to acting as a proto-oncogene or a potential suppressor in many types of cancer, the role of SRSF3 in autophagy may also be opposite in different cell models." (PMID 36764525, 2023). "SRSF3 may promote cancer invasion and metastasis via several mechanisms." (PMID 37416784, 2023). "SRSF3 may be a clinical therapeutic target for human pan-cancer." (PMID 35494088, 2022). "Therefore, the correlation between SRSF3 expression and the infiltration level of various immune cells among 33 human pan-cancer types was examined to assess whether SRSF3 can influence immune microenvironment of tumors or not." (PMID 35494088, 2022). "However, the expression and clinical values such as overall survival of SRSF3 in human pan-cancer still remain largely unknown." (PMID 35494088, 2022). "The associations of SRSF3 expression level and TMB and MSI among human pan-cancers were demonstrated and the results have shown that SRSF3 could act as an extra indicator for immune treatment assessment of cancer patients after management." (PMID 35494088, 2022). "In a significant proportion of cancers SRp20/SRSF3 is absent or mutated, suggesting that this mechanism may contribute to the high IR-A:IR-B ratio in cancer cells." (PMID 30453495, 2018). "Interestingly, SRSF1 is known to regulate a plethora of biological functions, further to splicing, within cells and is located in the middle of a self-regulatory network involving several splicing factors such as PTBP1 and SRSF3 that act as known oncoproteins in different types of cancer." (PMID 29415469, 2018). "RIF1 alternative splicing was regulated by a suite of RNA-binding proteins, including serine and arginine rich splicing factor 1 (SRSF1), SRSF3, and SRSF7 whose expression and occupancy on RIF1 pre-mRNA changed in response to DNA damage and in primary cancers." (PMID 41489901, 2025). "Using HCC tissue array assays we also found an increased SRSF3 protein expression in 110 samples of HCC (grade 2 and 3) compared to 10 samples of normal liver tissues, as seen in many other cancer tissues." (PMID 40568073, 2025). "By using mass spectrometry-based quantitative proteomics analysis, we discovered that strophanthidin (SPTD) upregulated 24 proteins, including Banf1 and LAMN, and downregulated 35 proteins, such as SRSF3 and COL1A5, in A549 cancer cells." (PMID 38398629, 2024). "Lastly, in a bid to identify the molecular effectors and pathways affected by miR-6741-3p-mediated regulation of SRSF3 in OSCC, we focused on two critical pathways namely, PI3K-AKT-MTOR and ERK/MAPK which are frequently deregulated in OSCC and other cancers." (PMID 38781195, 2024).
cancer (continued). "Consistently, SRSF3 knockdown induces cell cycle arrest in G2/M stage in U2OS and HeLa cancer cells." (PMID 37416784, 2023). "In cancer cells, PTBP1 and PTBP2 promote the skipping of an exon of SRSF3, therefore impairing the autoregulation of SRSF3." (PMID 36833284, 2023). "In cancer cells, oncogenic PTBP1 and PTBP2 proteins impair SRSF3 autoregulation by repressing SRSF3 exon 4 inclusion and significantly enhancing SRSF3 expression." (PMID 36505770, 2022). "However, the mechanisms of SRSF3 in pan-cancers are still unknown." (PMID 35494088, 2022). "Host RNA splicing factor SR proteins, including SRSF1(ASF/SF2), SRSF2 (SC35), SRSF3 (SRp20), and SRSF10 (SRp38/SRrp40), are also upregulated in HPV-positive cervical precancer lesions and cancer tissues." (PMID 35563334, 2022). "For example, SRSF3 acts as a PKM splicer and plays a positive role in cancer-specific energy metabolism in CRC." (PMID 35198444, 2022). "SRSF3 inhibits the usage of proximal 3’ splice site and the autoregulation, thus remarkably enhancing SRSF5 expression in cancer cells." (PMID 36505770, 2022). "Nevertheless, the decreased expression of SRSF3 in COAD, DLBC, KIRC, LUSC, OV, and THYM cancer patients were found that got poorer prognosis." (PMID 35494088, 2022). "According to the correlation analysis between SRSF3 and immune checkpoint gene expression, it can be found that SRSF3 is closely related to TNFSF14, TNFRSF14, TNFRSF25, CD276, NRP1, VSIR in a variety of malignant tumors (P <0.05)." (PMID 35494088, 2022). "As expected, KD of SRSF3 inhibited HCT‐116 and SW620 CRC cell growth, colony formation, migration, and invasion, similar to the cancer phenotypes mediated by SRSP KD or KO." (PMID 32440474, 2020). "For example, the PCBP1, SRSF3, and NIFK promotes cancer progression in metastasis or carcinogenesis." (PMID 32219019, 2020). "Here, we focussed on eIF4E, SRSF3, and UNR as examples of RNA regulons involved in cancer progression." (PMID 30455716, 2018). "SRSF3 silencing was noted to reduce the relative level of PDCD4 isoform 2, containing the partial PDCD4 intron 3 in distinct cancer cells." (PMID 27983653, 2016). "Cancer cells take advantage of high levels of PTBP1 and PTBP2 to impair the inclusion of exon 4, thereby allowing the overexpression of full length SRSF3 and promoting cell proliferation and transformation." (PMID 26416554, 2015). "The splicing regulator proteins SRSF1 (also known as ASF/SF2) and SRSF3 (also known as SRP20) belong to the SR family of proteins and can be upregulated in cancer." (PMID 23935626, 2013). "Nevertheless, the results of OS could be influenced by non-cancer according to deaths during the following period and thus the data from the TCGA were analyzed for correlation between DSS and the expression of SRSF3 among human pan-cancer." (PMID 35494088, 2022). "The immunohistochemistry (IHC) results showed that KHSRP, SRSF3 and RBM9 were located in nucleus, and the expression of SRSF3 and RBM9 were significantly lower in cancer than normal thyroid, while there was no significantly different between KHSRP, NOVA2 and PTBP2 in carcinoma and normal tissues." (PMID 34722250, 2021). "However, in cancer cells, the hnRNP splicing factors PTBP1 and PTBP2, are able to impair this negative feedback mechanism by binding to an ESS in exon 4 of SRSF3, inhibiting its inclusion and promoting SRSF3 upregulation." (PMID 33321981, 2020). "It was reported that SRSF3 affected the expression levels of miR-132-3p and miR-212-3p, including both their primary form and their mature form, by controlling RE1-silencing transcription factor (REST) in cancer cells." (PMID 33072610, 2020).
cancer (continued). "SRSF3 reportedly modulated the alternative splicing of several apoptosis-related genes, such as caspase-2 (Casp2), programmed cell death 4 (PDCD4), and homeodomain-interacting protein kinase-2 (HIPK2) in distinct cancer cells." (PMID 27983653, 2016). "In summary, we found that autoregulaton of SRSF3 expression involves inclusion of exon 4, which is regulated by PTBP1 and PTBP2 binding to an ESS motif, and that this regulatory process is impaired in OSCC cancer cells." (PMID 26416554, 2015). "A number of the SR proteins have been found to have roles in cancer, amongst them, SRSF1 and SRSF3." (PMID 23935626, 2013). "As we identified SRSF3 as a direct target for miR-6741-3p, we proposed that the downregulation of miR-6741-3p might also be responsible for the increased expression of SRSF3 in OSCC and other cancers and might play a critical role in tumorigenesis." (PMID 38781195, 2024). "Additionally, the significance of SRSF3 expression in cancer progression was emphasized by the gap over 3 years between survival times (according to DFI) of different patient group with high and low expression of SRSF3." (PMID 35494088, 2022). "However, there is no study exploring the oncogenic of role SRSF3 comprehensively in human pan-cancer." (PMID 35494088, 2022). "Several important roles in cancer development have been recently found to be played by other splicing factors, such as the function of FOX2, RBM4, and CELF2 as tumour suppressors, the oncogenic effect of CELF1, or the regulation of SRSF3 splicing patterns by PTBP1 and PTBP2." (PMID 28374191, 2017). "It is even possible that the new data on cancer cells might differ from that on non-cancer cells, reflecting the oncogenic effects vs. tumor suppressor effects when expressed at high vs. low levels of SRSF3." (PMID 33072610, 2020).
tumor (67 papers, 2007 to 2025). "Roles of SRSF3 in anti-tumor immune response can be exemplified by YAP1 (Yes-associated protein 1), an oncogenic co-transactivator." (PMID 37416784, 2023). "Tumor‐associated splicing events correlated with worse survival (hazard ratios 1.5 to 2.17, p‐values 2.54e‐4 to 0.0349) implying that SRSF3‐dependent splicing activity is associated with better survival." (PMID 35615981, 2022). "To determine the role of SRSF3 during tumor progression, we performed loss and gain-of-function assays using lentivirus-mediated knockdown and overexpression systems in SW480 and 786-O cells in vitro and in vivo." (PMID 35494088, 2022). "Increased SRSF3 expression levels have been associated with an increased tumour grade in ovarian cancer." (PMID 23935626, 2013). "Notwithstanding, due to the multiplicity of interactions of SRSF3 and its multi-functional association, it can promote tumor alterations via other unknown mechanisms." (PMID 35494088, 2022). "Silencing these splicing factors reduced the aggressive behavior of U-87 MG and U-118 MG tumor cells and induced apoptosis, particularly when SRSF3 was silenced in vitro." (PMID 39915450, 2025). "A significant delay (p = 0.0112) in tumor development in Erbb2 mice with Srsf3 KO was observed when compared to Erbb2 mice with WT Srsf3." (PMID 40568073, 2025). "Consistently, inhibition of SRSF3 induces cellular senescence as a tumor-suppressive mechanism, as previously shown by us." (PMID 40568080, 2025). "In contrast, Srsf3 was found to be tumor suppressive and played an important sex-disparity role in the development of liver tumor during 18 months of observation." (PMID 40568073, 2025). "Non-coding RNAs reciprocally regulate FN1: tumor-suppressive hsa_circ_0050386 binds SRSF3 to block FN1 pre-mRNA splicing and suppress metastasis, while oncogenic Lnc-PDZD7-3 upregulates FN1 to enhance MMP2/9-mediated invasion." (PMID 41301482, 2025). "In our literature review, we found that genes such as SRSF3, TCF7L2, FOXP1, and CEP55 have been documented to be associated with epithelial-mesenchymal transition (EMT) in tumor cells." (PMID 38254188, 2024). "A positive relationship between SRSF3 expression and tumor grading.A significantly higher expression of the SR in patients with lymphatic metastasisBetter overall survival rates." (PMID 39000035, 2024). "As a proto-oncogene, overexpression of SRSF3 has proven to induce cell transformation and tumor formation and maintenance." (PMID 37416784, 2023). "We observed remarkable reductions in tumor volume and weight in SRSF3-knockdown groups compared with the control groups." (PMID 37558679, 2023). "The level of SRSF3 overexpression in LIM1215 cells corresponded to the levels observed in primary tumours." (PMID 37306233, 2023). "Sixty per cent of the tumours analysed displayed this signature of SRSF3‐miR‐17/20a‐CDKN1A expression." (PMID 37306233, 2023). "We also analysed TCGA COAD data, including mRNA expression data for 459 tumour and 41 normal samples and miRNA expression data for 272 tumour and eight normal samples (version 2016_01_28) for SRSF3‐miR‐17/20a‐CDKN1A expression signature." (PMID 37306233, 2023). "Analysis of tumour and adjacent normal tissue from 25 CRC patients not subjected to chemo‐ or radiotherapy demonstrated significantly increased SRSF3 mRNA levels in the tumour compared with their paired normal tissue." (PMID 37306233, 2023). "Our results demonstrate that SRSF3 markedly fosters GC survival and inhibits GC apoptosis in dairy goats, which highlighted the distinctive antiapoptotic effect of SRSF3 on non-tumor tissue." (PMID 37240097, 2023). "Functional assay showed that SRSF3 is correlated to cell apoptosis therefore affecting tumor progression." (PMID 35494088, 2022).
tumor (continued). "In this study, we demonstrated that SRSF3 was highly expressed in CRC tissues and tumor cells around blood vessels and verified that SRSF3 played important roles in the angiogenesis of CRC." (PMID 35198444, 2022). "A correlation with progression of disease was recognized for ACC, KIRP, LIHC, and UCEC, for which patients with high expression level of SRSF3 triggered from early tumor recurrence and these results were validated by immunohistochemistry (P <0.05)." (PMID 35494088, 2022). "SRSF3, an important member of the serine/arginine-rich protein (SRp) family, is highly expressed in various tumors and plays an important role in tumor cell proliferation, migration and invasion." (PMID 35198444, 2022). "Previous studies consider SRSF3 to be a proto-oncogene that is frequently overexpressed in many tumor tissues, such as colon, breast, stomach, and skin." (PMID 35501301, 2022). "Another study showed that a 130aa-peptide known as SRSP encoded by the lncRNA LOC90024 plays a role in modulating mRNA splicing by binding to SRSF3 and thereby promoting the proliferation, migration, and invasion of tumor cells." (PMID 36309750, 2022). "SRSF3 was also found to significantly regulate the expression of at least 20 miRNAs, many of which are oncogenic or tumor suppressive." (PMID 35463320, 2022). "SRSF3 was reported that its expression level has multi-biological function in tumor cells proliferation and metabolism, metastasis, apoptosis, cell cycle and also immune response." (PMID 35494088, 2022). "In ACC, KIRP and UCEC cancer, upregulated expression of SRSF3 was associated with worse disease-free interval (DFI), representing a mechanism in promoting progression of tumor." (PMID 35494088, 2022). "Che and Fu have disclosed that SRSF3 plays a section in promoting cell viability in tumor cells, with higher levels in tumor cells with a high degree of malignancy, and the conclusions revealed in this study are similar to theirs." (PMID 36237584, 2022). "ANXA1 serves as a tumor suppressor expressing very little in the proliferating basal OS cells which is negatively regulated by the oncogene serine/arginine-rich splicing factor 3 (SRSF3)." (PMID 33291071, 2020). "That is, the overexpression of SRSF3 in tumors switches splicing variants of HER2 mRNA from p100 to Δ16HER2, leading to tumor progression." (PMID 33072610, 2020). "Of course, the effects of SRSF3 in the functions of indole derivatives in tumor cells need extensive analysis." (PMID 33072610, 2020). "The human CRC LoVo cells bearing SRSF3 shRNA or control shRNA were separately implanted subcutaneously into nude mice to allow tumor formation." (PMID 32308565, 2020). "SRSF3 is highly expressed in many tumor tissues, such as the thyroid, ovary, lung, colon, breast, stomach, skin and bladder 15, 24-26." (PMID 32284746, 2020). "SLU7 knockdown not only increases the abnormal expression of truncated SRSF3 but also leads to the altered proliferation and abnormal metabolism of tumor cells." (PMID 32284746, 2020). "As expected, these analyses confirmed in CMS4 subtype the higher expression of SERPINA 1, whereas the expression of SRSF3 (spliceosome) was down‐regulated in this type of tumours." (PMID 31560832, 2019). "In particular, the cell silenced SRSF3 by intravenously injected siR-SRSF3 inhibited tumor growth in DLD-1 cell-xenografted mice." (PMID 30279379, 2018). "Through genome-wide analyses of SRSF3 target genes, SRSF3 is reported to significantly influence the expression of a subset of oncogenic or tumor suppressive miRNAs." (PMID 28039456, 2017). "Knockout studies indicated that SRSF3 is essential for mouse development, hepatocyte differentiation, and metabolic function, as well as tumor cell proliferation and maintenance." (PMID 29254178, 2017).